ENSG00000268400 (novel protein)
Gene: Protein-coding gene on chromosome 19 (7,629,796 to 7,647,477, forward strand). Ensembl gene ENSG00000268400.
Genetic constraint (gnomAD): Missense variants: 87 observed, 85.68 expected, observed/expected ratio (o/e) 1.02, 90% interval 0.85 to 1.21. Synonymous variants: 29 observed, 29.26 expected, observed/expected ratio (o/e) 0.99, 90% interval 0.74 to 1.35.